LNCPRESS1 (lncRNA p53 regulated and ESC associated 1)
Gene: Long non-coding RNA gene on chromosome 7 (101,299,552 to 101,304,587, forward strand). Ensembl gene ENSG00000232301.
Diseases named in the same sentence as LNCPRESS1 in open-access papers:
LNCPRESS1 is named in the same sentence as 5 diseases in open-access papers, as found by Europe PMC text mining. Sharing a sentence is not in itself a finding about the gene and the disease. The quoted sentences say what the papers report.
lung carcinoma (2 papers, 2022 to 2023). "EMSLR regulated the cell proliferation and differentiation by repressing the promoter activity of LncPRESS1 in lung cancer cell." (PMID 38017579, 2023). "We discovered that EMSLR represses the promoter activity of another lncRNA, LncPRESS1, which is located 6.9 kb upstream of EMSLR and they display an inverse expression pattern in lung cancer cell lines." (PMID 35169159, 2022).
cancer (1 paper, 2022). A tumor composed of atypical neoplastic, often pleomorphic cells that invade other tissues. "Thus, we propose that MYC-EMSLR-LncPRESS1 pathway is functional in cancer cells based on the following results: First, LncPRESS1 was upregulated after depletion of EMSLR." (PMID 35169159, 2022).
LNCPRESS1 also shares sentences with these, for which no sentence is quoted: lung adenocarcinoma (1 paper); non-small cell lung carcinoma (1); tumor (1).